EEF1D (eukaryotic translation elongation factor 1 delta)
Description:
[Isoform 1]: EF-1-beta and EF-1-delta stimulate the exchange of GDP bound to EF-1-alpha to GTP, regenerating EF-1-alpha for another round of transfer of aminoacyl-tRNAs to the ribosome. [Isoform 2]: Regulates induction of heat-shock-responsive genes through association with heat shock transcription factors and direct DNA-binding at heat shock promoter elements (HSE).
Synonyms: EF1D; EF-1D; FLJ20897; FP1047; NEDTCHAL
Tractability: PROTAC: ubiquitination databases record sites on it; its protein half-life has been measured.
Gene: Protein-coding gene on chromosome 8 (143,579,697 to 143,599,541, reverse strand). Ensembl gene ENSG00000104529.
Subcellular location: Nucleus (Isoform 2)
Subcellular location (Human Protein Atlas): Nucleoli fibrillar center; Nucleoplasm
Pathways (Reactome):
Metabolism of proteins: Eukaryotic Translation Elongation
Gene Ontology:
Molecular function: cadherin binding; protein binding; guanyl-nucleotide exchange factor activity; translation factor activity, RNA binding; translation elongation factor activity
Biological process: cellular response to ionizing radiation; translational elongation
Cellular component: cytoplasm; endoplasmic reticulum; fibrillar center; nucleoplasm; nucleus; cytosol; eukaryotic translation elongation factor 1 complex
Genetic constraint (gnomAD): Loss-of-function variants: 47 observed, 55.24 expected, observed/expected ratio (o/e) 0.85, 90% interval 0.67 to 1.09. The upper end of that interval is the gene's LOEUF score, 1.09, which puts it in group 4 of 6, group 1 being the genes least tolerant of losing a copy. Missense variants: 907 observed, 828.03 expected, observed/expected ratio (o/e) 1.1, 90% interval 1.04 to 1.16. Synonymous variants: 412 observed, 347.75 expected, observed/expected ratio (o/e) 1.18, 90% interval 1.09 to 1.28.
Homologues: Orthologues: chimpanzee EEF1D (98% identical), macaque PYCR3 (91% identical), rat Eef1d (87% identical), mouse Eef1d (85% identical), guinea pig EEF1D (84% identical), dog EEF1D (83% identical), pig EEF1D (77% identical), zebrafish eef1db (28% identical), zebrafish eef1da (23% identical), Drosophila melanogaster eEF1delta (21% identical), Drosophila melanogaster eEF1beta (18% identical), Caenorhabditis elegans eef-1B.1 (16% identical). Paralogues in human: EEF1B2 (21% identical), EFCC1 (13% identical).
Diseases named in the same sentence as EEF1D in open-access papers:
EEF1D is named in the same sentence as 62 diseases in open-access papers, as found by Europe PMC text mining. Sharing a sentence is not in itself a finding about the gene and the disease. The quoted sentences say what the papers report.
glioma (6 papers, 2018 to 2023). A benign or malignant brain and spinal cord tumor that arises from glial cells (astrocytes, oligodendrocytes, ependymal cells). "Taken together, these findings suggested that EEF1D was closely associated with the modulation of EMT progress in glioma cells, and inhibition of EEF1D could reverse the EMT characteristics of glioma cells." (PMID 33029523, 2020). "EEF1D has also been reported to be overexpressed in various tumors, such as glioblastoma, glioma, and lymphoma." (PMID 38332912, 2023). "In the present study, Western blot results revealed that PI3K, p-PI3K, Akt, and p-Akt in glioma cells transfected with EEF1D-siRNA were significantly lower than those transfected with NC-siRNA (P < 0.05)." (PMID 33029523, 2020). "As expected, EEF1D expression was significantly decreased in both U87 and A172 cells after transfection with EEF1D-siRNA, which in turn resulted in significant inhibition of glioma cell proliferation." (PMID 33029523, 2020). "Consistently, in the present study, we found that the expression of EEF1D, as indicated both by immunohistology staining and immunoblotting, was elevated and positively correlated with glioma grade." (PMID 33029523, 2020). "Overall, our results contribute to the knowledge of EEF1D effects on glioma and provide insights into the mechanism of glioma through mediating EMT and PI3K/Akt pathways." (PMID 33029523, 2020). "In summary, these results proposed that inhibition of EEF1D could suppress the cell growth and reduce the malignant phenotype-like proliferation, migratory, and invasion of glioma cells." (PMID 33029523, 2020). "In the present study, we found that EEF1D may play a role in the development of glioma through multiple pathways and provided new insights into the glioma initiation." (PMID 33029523, 2020). "Alteration of the processes induced by aberrant expression of EEF1D may impair the indispensable nucleic acid metabolism and translational deregulation and finally impede tumor cell survival and progression including glioma." (PMID 33029523, 2020). "Overall, our data provide evidence that EEF1D might serve as a potential therapeutic target for glioma." (PMID 33029523, 2020). "To investigate the influence of EEF1D on glioma cells, we constructed siRNA targeting EEF1D gene." (PMID 33029523, 2020). "Taken together, these results indicate that EEF1D and its partner proteins might play a critical role in glioma and serve as a potential therapeutic target of glioma." (PMID 33029523, 2020). "However, the detailed mechanism of EEF1D on glioma progression phenotype remains elusive and needs further investigation." (PMID 33029523, 2020). "Moreover, we also detected higher EEF1D expression in U87 and A172 glioblastoma cell lines among six commonly used glioma cell lines, so U87 and A172 glioblastoma cell lines were chosen for a further experiment." (PMID 33029523, 2020). "Furthermore, EEF1D may constitute a new prospect for a therapeutic target against human glioma." (PMID 33029523, 2020). "Glioblastoma and glioma dataset revealed that EEF1A1, EEF1G, EEF1D and EEF2 were significantly overexpressed in tumor tissues whereas EEF1A2 was significantly downregulated." (PMID 29342219, 2018). "It was demonstrated that EEF1D increases glioma proliferation and invasion via modifying the EMT process and that blocking EEF1D might reverse the EMT properties of glioma cells, decreasing cell growth and tumor progression." (PMID 37762559, 2023). "In the present study, we demonstrated for the first time that EEF1D may interact with other putative proteins to regulate cell proliferation, migration, and invasion through PI3K/Akt and EMT pathways in glioma." (PMID 33029523, 2020). "Our results suggested that EEF1D exerts its effect on glioma by promoting EMT and PI3K/Akt signaling pathways, which could be the potential mechanism by which EEF1D promotes tumor progression." (PMID 33029523, 2020).
glioma (continued). "In the present study, aberrant expression of EEF1D was confirmed in glioma samples in comparison with nontumor brain tissues." (PMID 33029523, 2020). "However, little has been uncovered regarding the underlying biological mechanisms correlated with EEF1D overexpression in glioma, and the involvement of EEF1D in glioma tumorigenesis has not yet been investigated." (PMID 33029523, 2020). "Taken together, these results indicated that EEF1D might bind to other proteins, like the protein of the EMT and PI3K/Akt pathway, to form a functional complex to regulate the progression phenotype of glioma cells." (PMID 33029523, 2020). "We also speculated that EEF1D may be involved in multiple major cell signaling pathways simultaneously like EMT and PI3K/Akt pathways to regulate cell survival, migration, and invasion in glioma." (PMID 33029523, 2020).
medulloblastoma (5 papers, 2006 to 2022). A malignant, invasive embryonal neoplasm arising from the cerebellum. "Genomic analysis in medulloblastoma also reveals that a higher EEF1D level was adversely associated with outcome." (PMID 33029523, 2020). "EEF1D has also been found to be upregulated in numerous malignant tumors, such as liver cancer, esophageal cancer, small cell lung cancer and medulloblastoma." (PMID 35672728, 2022). "EEF1D has also been reported to be upregulated in numerous other malignant tumors, such as liver cancer, esophageal cancer, small cell lung cancer and medulloblastoma." (PMID 35672728, 2022). "Nonetheless, our results suggest that better appreciation of the relative contributions of EEF1D, RPL30, RPS20, and their associated regulatory mechanisms will impact our understanding of medulloblastoma biology." (PMID 16968546, 2006). "We demonstrate that gain of 8q and expression levels of three 8q-mapped candidate genes (EEF1D, RPL30, RPS20) are associated with adverse outcome in medulloblastoma." (PMID 16968546, 2006). "Besides this canonical role, EEF1D was found overexpressed in many tumors, like hepatocarcinomas and medulloblastomas." (PMID 33029523, 2020). "Eukaryotic translation elongation factor 1 delta (EEF1D) has been linked with mediating epithelial mesenchymal transition (EMT) in oral squamous cell carcinoma and its overexpression is associated with worse overall survival and progression free survival in medulloblastoma." (PMID 29342219, 2018). "Alternatively, we assayed the expression of EEF1D, RPL30, and RPS20 with qRT-RTPCR in twelve available medulloblastoma specimens, including those analyzed by Affymetrix U133 Plus 2.0 microarrays." (PMID 16968546, 2006).
osteosarcoma (5 papers, 2018 to 2024). A usually aggressive malignant bone-forming mesenchymal neoplasm, predominantly affecting adolescents and young adults. "The aim of this study is to investigate the expression and role of EEF1D in osteosarcoma and to elucidate its underlying mechanisms." (PMID 29510727, 2018). "In the present study, we investigated the potential mechanisms underlying the role of EEF1D in osteosarcoma." (PMID 29510727, 2018). "The functions and underlying mechanisms of EEF1D were further investigated in osteosarcoma cells." (PMID 29510727, 2018). "Considering the composition of prognostic model, it is reported that EEF1D overexpression promotes osteosarcoma cell proliferation by facilitating Akt-mTOR and Akt-bad signaling." (PMID 38213729, 2024). "To explore the functional significance of EEF1D in osteosarcoma, we used si-EEF1D to knockdown EEF1D in osteosarcoma cells." (PMID 29510727, 2018). "To determine the role of EEF1D in osteosarcoma, we first examined EEF1D mRNA and protein expression levels in osteosarcoma and osteoblast cell lines by qRT-PCR and western blotting analysis." (PMID 29510727, 2018). "EEF1D knockdown using small interfering RNA (siRNA) was employed to analyze the role of EEF1D in osteosarcoma cell proliferation and cell cycle progression." (PMID 29510727, 2018). "In conclusion, we demonstrate for the first time that EEF1D is upregulated in human osteosarcoma cell lines and clinical tumor samples." (PMID 29510727, 2018). "EEF1D knockdown inhibited osteosarcoma cell proliferation, colony-forming ability, and cell cycle G2/M transition in vitro." (PMID 29510727, 2018). "In this study, we investigated the expression of EEF1D in human osteosarcoma samples and osteoblast cell lines." (PMID 29510727, 2018). "High expression of EEF1D is positively correlated with Enneking stage and the recurrence of osteosarcoma, and facilitates osteosarcoma cell proliferation." (PMID 29510727, 2018). "Together, the data shows that EEF1D knockdown attenuates osteosarcoma cell proliferation by inhibiting the G2/M transition." (PMID 29510727, 2018). "The expression of EEF1D in osteosarcomas and cell lines was evaluated by qRT-PCR, Western blotting and immunohistochemistry." (PMID 29510727, 2018). "Colony-forming assays were performed to determine the colony-forming capacity of osteosarcoma cells after EEF1D knockdown." (PMID 29510727, 2018). "EEF1D is upregulated in osteosarcoma and plays a tumor promoting role by facilitating Akt-mTOR and Akt-Bad signaling pathways." (PMID 29510727, 2018). "Our results demonstrated that knockdown of EEF1D hindered osteosarcoma cell proliferation and colony-forming ability by inhibiting the G2/M cell cycle transition." (PMID 29510727, 2018). "However, the role and underlying molecular mechanisms of EEF1D in osteosarcoma remain unclear." (PMID 29510727, 2018). "In this study, we demonstrated that EEF1D, a subunit of the eEF1 complex, was upregulated in osteosarcoma cell lines and clinical tumor samples in comparison with the corresponding adjacent non-tumor tissues." (PMID 29510727, 2018). "Taken together, these results indicate that EEF1D is upregulated in osteosarcoma and potentially plays an important role in osteosarcoma progression." (PMID 29510727, 2018). "To determine the potential mechanism by which EEF1D affects the proliferation of osteosarcoma cells, we screened for changes of intracellular signaling molecules resulted from EEF1D knockdown in MNNG/HOS and U2OS cells." (PMID 29510727, 2018). "A five-day growth curve analysis using CCK-8 assay showed that knockdown of EEF1D significantly inhibited the growth of osteosarcoma cells." (PMID 29510727, 2018). "Compared with the osteoblast cell line, the osteosarcoma cell lines expressed significantly higher levels of both EEF1D mRNA and protein." (PMID 29510727, 2018).
osteosarcoma (continued). "In the present study, we found that the expression of EEF1D, as indicated by IHC staining, was positively correlated with osteosarcoma recurrence and Enneking stage." (PMID 29510727, 2018). "We found that reduction in EEF1D downregulated the Akt-mTOR and Akt-Bad signaling pathways in osteosarcoma cells." (PMID 29510727, 2018). "Knockdown of EEF1D impaired osteosarcoma cell proliferation and colony-forming ability, and led to G2/M cell cycle arrest." (PMID 29510727, 2018). "Mechanistically, EEF1D exerts oncogenic effects by maintaining the Akt-mTOR and Akt-Bad signaling pathways in osteosarcoma." (PMID 29510727, 2018). "Here, we found that EEF1D was upregulated in human osteosarcoma." (PMID 38077434, 2023). "We found that in OS cells, EEF1D knockdown resulted in G2/M arrest, suggesting EEF1D may affect cell cycle progression in osteosarcoma via different mechanisms." (PMID 29510727, 2018). "Our results suggest that EEF1D exerts its effect on osteosarcoma by promoting Akt-mTOR and Akt-Bad signaling pathways, which could be the mechanism by which EEF1D promotes tumor progression." (PMID 29510727, 2018). "Taken together, out data support that EEF1D may play an important role in osteosarcoma cell growth by enhancing the Akt-mTOR and Akt-Bad signaling pathways." (PMID 29510727, 2018). "Overall, our data provide evidence that EEF1D is a potential therapeutic target for osteosarcoma." (PMID 29510727, 2018). "Notably, we found that EEF1D expression correlated positively with the Enneking stages and recurrence of osteosarcoma." (PMID 29510727, 2018). "The expression of EEF1D was found to be up-regulated in human osteosarcoma tissues and cell lines." (PMID 29510727, 2018). "EEF1D was found to be overexpressed in osteosarcoma cell lines and tissues." (PMID 29510727, 2018). "Whether EEF1D directly or indirectly affects CyclinD1/Cdk4 or Cyclin B1/Cdk1 activity in osteosarcomas remains to be investigated." (PMID 29510727, 2018). "We further examined whether EEF1D knockdown could affect the Akt-mTOR and Akt-Bad signaling pathways in osteosarcoma cells using Western blotting analysis, and the results revealed that EEF1D knockdown inhibited the phosphorylation of Akt, mTOR, and Bad." (PMID 29510727, 2018). "Dysregulation of eukaryotic translation elongation factor 1 delta (EEF1D) in cancers has been reported; however, the role and mechanisms of EEF1D in osteosarcoma remain poorly understood." (PMID 29510727, 2018). "EEF1D expression levels were higher in osteosarcoma tissue samples than in the corresponding non-tumor tissues (P = 0.018)." (PMID 29510727, 2018). "To further determine the clinicopathological significance of EEF1D in osteosarcoma, we performed IHC analysis of EEF1D in 50 human osteosarcoma tissue samples and the corresponding non-tumor tissues." (PMID 29510727, 2018). "EEF1D expression was significantly upregulated in 60% (12/20) of osteosarcoma tissues compared with that in adjacent non-tumor tissues." (PMID 29510727, 2018). "Further, EEF1D mRNA expression levels were investigated in 20 paired osteosarcoma and adjacent non-tumor tissue samples." (PMID 29510727, 2018). "In addition, the cell apoptosis assay showed that knockdown of EEF1D did not affect the cell apoptosis in osteosarcoma cells." (PMID 29510727, 2018).
breast carcinoma (3 papers, 2018 to 2023). "To obtain evidence regarding the effects of serum factors on the expression of the CanCord34 genes, we examined the effects of serum starvation for 72 h on the levels of EEF1D, TIGD5, C8ORF73/MROH6, and BOP1 in the breast cancer SKBR-3, cervical cancer SiHa, and neuroblastoma IMR-32 cell lines." (PMID 36497066, 2022). "The higher EEF1D expression on the other hand, predicted worse RFS in breast cancer patients." (PMID 29342219, 2018).
cervical cancer (3 papers, 2021 to 2025). A primary or metastatic malignant neoplasm involving the cervix. "The expression level of EEF1D increased with advanced M stage, which implied that it’s expression level may be correlated with the organ metastasis ability of cervical cancer." (PMID 34863153, 2021). "It is displayed in kaplan–Meier curves that higher expression level of EEF1D, CTU1, EIF3C, WDR43, NUFIP1, ZC3HAV1L and PRPF40B indicated a lower overall survival of cervical cancer patients." (PMID 34863153, 2021).
glioblastoma (3 papers, 2018 to 2023). The most malignant astrocytic tumor (WHO grade IV). "EEF1D was overexpressed in Rickman’s study for astrocytoma and also in TCGA dataset of Glioblastoma." (PMID 29342219, 2018).
lung carcinoma (3 papers, 2018 to 2022). "A proteomic analysis of adriamycin-resistant variants of the DLKP lung cancer cell line revealed that EEF1D levels correlated with the invasive potential of these cells." (PMID 29510727, 2018). "Overexpression of most factors predicted a poor prognosis in breast (EEF1D, EEF1E1, and EEF2) and lung cancer (EEF1A2, EEF1B2, EEF1G, EEF1E1) in KM analysis." (PMID 29342219, 2018). "Overexpression of many factors predicted poor prognosis in breast (EEF1D, EEF1E1, EEF2) and lung cancer (EEF1A2, EEF1B2, EEF1G, EEF1E1)." (PMID 29342219, 2018).
Alzheimer disease (2 papers, 2023). A progressive, neurodegenerative disease characterized by loss of function and death of nerve cells in several areas of the brain leading to loss of cognitive function such as memory and language. "With FRA10AC1 being well-connected by three binary interactors, namely VPS29, GATD3A, and EEF1D, to APP (amyloid β A4 precursor protein), the previously reported information characterizing two FRA10AC1 SNPs biomarkers of Alzheimer’s disease is further supported." (PMID 36980839, 2023).
chondrosarcoma (2 papers, 2018 to 2020). A malignant cartilaginous matrix-producing mesenchymal neoplasm arising from the bone and soft tissue. "Recently, the role of EEF1D in tumors, including chondrosarcoma and papillary renal cell carcinoma, has been investigated, and mutation of EEF1D may contribute to the tumorigenesis of Papillary renal cell carcinoma." (PMID 29510727, 2018).
colon cancer (2 papers, 2018 to 2023). "Another comparative proteomics analysis of differentially-expressed proteins between Chinese left- and right-sided colon cancer showed that EEF1D expression was higher in the right-sided colon cancer." (PMID 29510727, 2018).